STX1B (syntaxin 1B)
Description:
Potentially involved in docking of synaptic vesicles at presynaptic active zones. May mediate Ca(2+)-regulation of exocytosis acrosomal reaction in sperm (By similarity).
Synonyms: STX1B1; STX1B2; GEFSP9
Tractability: Antibody: its Gene Ontology location is reachable by antibodies, with high confidence; UniProt predicts a signal peptide or a membrane-spanning region. PROTAC: ubiquitination databases record sites on it; its protein half-life has been measured.
Gene: Protein-coding gene on chromosome 16 (30,989,256 to 31,010,672, reverse strand). Ensembl gene ENSG00000099365.
Subcellular location: Membrane (Isoform 1); Nucleus (Isoform 2); Cytoplasm, cytoskeleton, microtubule organizing center, centrosome; Cytoplasm, cytoskeleton, spindle
Subcellular location (Human Protein Atlas): Nuclear membrane; Vesicles
Pathways (Reactome):
Developmental Biology: LGI-ADAM interactions
Disease: Toxicity of botulinum toxin type C (botC)
Gene Ontology:
Molecular function: protein binding; protein kinase binding; SNARE binding; signaling receptor binding; SNAP receptor activity
Biological process: exocytosis; negative regulation of macropinocytosis; negative regulation of neuron projection development; neurotransmitter secretion; positive regulation of excitatory postsynaptic potential; positive regulation of neurotransmitter secretion; regulation of gene expression; regulation of synaptic activity; regulation of synaptic vesicle priming; synaptic vesicle fusion to presynaptic active zone membrane; calcium ion-regulated exocytosis of neurotransmitter; intracellular protein transport; negative regulation of synaptic vesicle recycling; positive regulation of spontaneous neurotransmitter secretion; spontaneous neurotransmitter secretion; synaptic vesicle exocytosis; vesicle-mediated transport
Cellular component: cytosol; membrane; plasma membrane; presynaptic active zone membrane; presynaptic membrane; synaptic vesicle membrane; axon; centrosome; neuromuscular junction; nucleus; presynapse; spindle
Genetic constraint (gnomAD): Loss-of-function variants: 6 observed, 38.48 expected, observed/expected ratio (o/e) 0.16, 90% interval 0.084 to 0.31. The upper end of that interval is the gene's LOEUF score, 0.31, which puts it in group 1 of 6, group 1 being the genes least tolerant of losing a copy. Missense variants: 197 observed, 392.86 expected, observed/expected ratio (o/e) 0.5, 90% interval 0.45 to 0.56. Synonymous variants: 135 observed, 146.7 expected, observed/expected ratio (o/e) 0.92, 90% interval 0.8 to 1.06.
Gene-disease validity (ClinGen):
ClinGen rates the evidence that STX1B causes each of these diseases.
generalized epilepsy with febrile seizures plus (autosomal dominant): Definitive. A familial epilepsy syndrome in which family members display a seizure disorder from the generalized epilepsy with febrile seizures plus spectrum which ranges from simple febrile seizures (FS) to the more severe phenotype of myoclonic-astatic epilepsy (MAE) or Dravet syndrome (DS).
Homologues: Orthologues: dog STX1B (100% identical), guinea pig STX1B (100% identical), mouse Stx1b (100% identical), macaque STX1B (98% identical), rat Stx1b (97% identical), zebrafish stx1b (96% identical), pig STX1B (93% identical), chimpanzee STX1B (88% identical), tropical clawed frog stx1b (87% identical), Drosophila melanogaster Syx1A (68% identical), rabbit STX1B (62% identical), Caenorhabditis elegans unc-64 (59% identical). Paralogues in human: STX1A (83% identical), STX2 (64% identical), STX3 (61% identical), STX4 (47% identical), STX11 (33% identical), STX19 (30% identical), STX5 (27% identical), STX16 (24% identical), STX12 (24% identical), STX17 (20% identical), STX7 (20% identical), TSNARE1 (14% identical).
Diseases named in the same sentence as STX1B in open-access papers:
STX1B is named in the same sentence as 51 diseases in open-access papers, as found by Europe PMC text mining. Sharing a sentence is not in itself a finding about the gene and the disease. The quoted sentences say what the papers report.
epilepsy (19 papers, 2017 to 2025). A brain disorder characterized by episodes of abnormally increased neuronal discharge resulting in transient episodes of sensory or motor neurological dysfunction, or psychic dysfunction. "In the subset of the patients, genetic testing revealed a specific cellular pathology (e.g., STX1B or SCN1A) as the underlying cause of their epilepsy." (PMID 39137987, 2024). "Clinical reports show that patients that harbor Stx1b mutations commonly present with epilepsy, frequently with febrile seizures, and developmental delay." (PMID 37066095, 2023). "Our current study identified a protective role for the microtubule-associated protein syntabulin in epilepsy and revealed for the first time the molecular mechanism of syntabulin-dependent STX1B synaptic trafficking in maintaining E/I balance in epilepsy." (PMID 37349285, 2023). "Compared to the mutations of its binding partner Munc18-1, which results in DEEs with an early onset epilepsy (Ohtahara syndrome or West syndrome), missense mutations in Stx1b cause DEE which presents with a later onset epileptic disorder." (PMID 37066095, 2023). "Variants of STX1B provoke fever-associated epilepsies of variable severity including Epilepsy with Myoclonic-Atonic Seizures." (PMID 34842787, 2021). "Here we showed that rs140820592 in the Syntaxin 1B-coding gene STX1B was significantly associated with the risks of epilepsy (drug-resistant epilepsy + drug-responsive epilepsy) and drug-resistant epilepsy." (PMID 34305610, 2021). "We found that the STX1B rs140820592 was significantly associated with the risk of drug-resistant epilepsy at the genetic and expressional levels, suggesting a role of STX1B in epilepsy treatment." (PMID 34305610, 2021). "The STX1B rs140820592 was associated with reduced risks for epilepsy and drug-resistant epilepsy, likely by regulating STX1B expression in brain tissues." (PMID 34305610, 2021). "In this study, we investigated the associations between seven STX1B tagging SNPs and treatment response in patients with epilepsy in Han Chinese, and then conducted brain expression quantitative trait loci (eQTL) analysis." (PMID 34305610, 2021). "Loss‐of‐function mutations in STX1B have been identified in patients with fever‐associated epilepsies of variable severity." (PMID 32783192, 2020). "Another genome-wide mega-analysis that included 15,212 people with epilepsy and 29,677 controls, found a significant association of rs1046276 (STX1B) at 16p11.2 locus with JME." (PMID 33096746, 2020). "Variants in STX1B are protean and contribute to many different epilepsy phenotypes, similar to SCN1A, the most important gene associated with fever-associated epilepsies." (PMID 30737342, 2019). "This work suggests a role for ultrarare STX1B variants in the pathogenesis of a broad range of both common and rare epilepsies." (PMID 30737342, 2019). "Variants in the STX1B gene contribute to many distinct epilepsy phenotypes." (PMID 38003627, 2023). "Associations between STX1B SNP genotypes and drug-resistant epilepsy." (PMID 34305610, 2021). "STX1B is an emerging epilepsy gene; mutations are expected to affect synaptic function." (PMID 32783192, 2020). "We demonstrate that STX1B variants are linked to 4 different epilepsy phenotypes." (PMID 30737342, 2019). "In summary, PTZ induces an epilepsy-like seizure, including photosensitive seizures in zebrafish, which may be partially mediated by STX1B deficiency." (PMID 30534049, 2018). "However, the role of STX1B SNPs in epilepsy treatment remains unknown, so it is necessary to explore the genetic association of STX1B SNPs with treatment response in patients with epilepsy in a Han Chinese population." (PMID 34305610, 2021). "However, the role of STX1B single nucleotide polymorphisms (SNPs) in epilepsy treatment remains unknown." (PMID 34305610, 2021). "Variant in STX1B may result in hyper-excitability of neuron giving rise to epilepsy." (PMID 33096746, 2020).
epilepsy (continued). "Therefore, we speculate that BBR might be able to suppress an epilepsy-like seizure by upregulating STX1B expression and also that the level of STX1B is associated with seizure outlook." (PMID 30534049, 2018). "One individual with uDEE displayed hypermethylation of the promoter region and TSS of STX1B (MIM: 601485), an established epilepsy gene known to cause generalized epilepsy with febrile seizures plus (GEFs + )." (PMID 39107278, 2024). "These evidences suggest that TFAP2A regulates syntabulin expression in epilepsy and STX1B expression in synaptosomes, and affects neural excitability." (PMID 37349285, 2023). "In line with to these findings, our results suggest that syntabulin positively regulates the localization and expression of STX1B at synapses and subsequently affects synaptic transmission to participate in the development of epilepsy." (PMID 37349285, 2023). "This is a study combining genetic association and eQTL analyses in brain tissues and blood samples to comprehensively evaluate the relationship between the STX1B gene and epilepsy treatment." (PMID 34305610, 2021). "Deficits in the subunits of the core complex (synaptobrevin-2, syntaxin-1B and SNAP-25), Munc18-1 and complexin-1 are mainly associated with an overlapping spectrum of developmental delay, intellectual disability, epilepsy, and movement disorders." (PMID 35095745, 2021). "In this study, we used PTZ to establish a zebrafish seizure model and researched STX1B functions in epilepsy-like seizures, including photosensitive seizures." (PMID 30534049, 2018). "We found that the stx1b gene expression decrease that accompanies epilepsy-like seizure aggravation, was induced by PTZ, and that STX1B increase and the alleviation of a seizure were observed under treatment of the anti-epilepsy drug VPA." (PMID 30534049, 2018). "We found that BBR can promote the expression of STX1B directly or indirectly and alleviate epilepsy-like seizures, especially photosensitive seizures in PTZ-induced seizure zebrafish larvae." (PMID 30534049, 2018). "TFAP2-syntabulin-STX1B axis is a critical pathway in epilepsy, thus may provide a potential new target for epilepsy treatment and drug development." (PMID 37349285, 2023). "In summary, rs140820592 may decrease the risks of epilepsy and drug-resistant epilepsy by regulating STX1B gene expression in human brain tissues." (PMID 34305610, 2021). "We provide multiple lines of evidence that the STX1B rs140820592 may decrease the risks of epilepsy (drug-resistant epilepsy + drug-responsive epilepsy) and drug-resistant epilepsy by regulating STX1B expression." (PMID 34305610, 2021). "Furthermore, syntabulin-dependent STX1B trafficking and synaptic delivery is critical for presynaptic neurotransmitter release and E/I balance, which protects the brain from epilepsy and may be a potential therapeutic target." (PMID 37349285, 2023). "Therefore, STX1B may be involved in epilepsy and drug responsiveness by regulating synaptic vesicle exocytosis." (PMID 34305610, 2021). "The transcription of stx1b was inhibited by PTZ but rescued by valproate, a broad-spectrum epilepsy treatment drug." (PMID 30534049, 2018). "Overall, we show for the first time that syntabulin transits more STX1B (but not STX1A) to the excitatory/inhibitory presynaptic membrane in epilepsy, suppressing neuronal hyperexcitability." (PMID 37349285, 2023). "Here, using biochemical, behavioral, and electrophysiological approaches, we show that syntabulin plays a protective role in epilepsy by interacting with STX1B, but not STX1A, and mediating its delivery to the synapse." (PMID 37349285, 2023). "Third, in this study, only STX1B gene was included, and other important epilepsy genes were not included in our study." (PMID 34305610, 2021).
epilepsy (continued). "These experiments suggested that syntabulin may affect epilepsy by transporting more STX1B rather than affecting STX1B expression." (PMID 37349285, 2023).
Parkinson disease (6 papers, 2018 to 2025). A progressive degenerative disorder of the central nervous system characterized by loss of dopamine producing neurons in the substantia nigra and the presence of Lewy bodies in the substantia nigra and locus coeruleus. "SNP rs7194347 overlaps with an enhancer region and may perturb the expression of STX1B whose methylation and expression changes are associated with Parkinson’s disease." (PMID 29378629, 2018).
generalized epilepsy (4 papers, 2022 to 2024). Epilepsy that is characterized by generalized seizure types and may have typical interictal and/or ictal EEG findings that accompany generalized seizure types (for example generalized spike-wave). "We identified three pathogenic or likely pathogenic mutations in the SNARE domain of STX1B in ClinVar of which V216E and G226R are associated with generalized epilepsy with febrile seizures plus, type 9." (PMID 38225382, 2024). "Interestingly, this individual showed additional features such as tremor and cerebellar ataxia that are not typical symptoms of STX1B-related generalized epilepsy with febrile seizures." (PMID 36564538, 2023).
autism (3 papers, 2019 to 2021). Persistent deficits in social interaction and communication and interaction as well as a markedly restricted repertoire of activity and interest as well as repetitive patterns of behavior. "For example, two genes within the autism-associated 16p11.2 region, SEZ6L2 and DOC2A, as well as the febrile seizure-associated gene STX1B, were downregulated in carriers of the 16p12.1 deletion." (PMID 34657631, 2021).
epilepsy syndrome (3 papers, 2019 to 2023). A syndrome that has a characteristic cluster of clinical features and/or lectroencephalographic (EEG) findings that reflect underlying epileptic activity. "Mostly truncating, but also several missense variants in STX1B are known to cause a childhood epilepsy syndrome with both febrile and afebrile seizures, typically with a benign course and good response to treatment." (PMID 36564538, 2023). "Mutations in syntaxin 1b (Stx1b), encoding a presynaptic protein, cause fever-associated epilepsy syndromes." (PMID 35269418, 2022). "The current study expands the number of reported patients with STX1B-related epileptic syndromes and describes 17 new variants." (PMID 30737342, 2019). "The aim of this study was to expand the spectrum of epilepsy syndromes related to STX1B, encoding the presynaptic protein syntaxin-1B, and establish genotype-phenotype correlations by identifying further disease-related variants." (PMID 30737342, 2019).
Cognitive impairment (2 papers, 2021). Abnormal cognition is characterized by deficits in thinking, reasoning, or remembering. "However, dysfunctions in STX1B and GOSR2 are less commonly associated with developmental delay, as most of the affected individuals don't show intellectual impairment." (PMID 35095745, 2021).
Seizure (2 papers, 2018 to 2024). A seizure is an intermittent abnormality of nervous system physiology characterized by a transient occurrence of signs and/or symptoms due to abnormal excessive or synchronous neuronal activity in the brain. "This indicates that STX1B decline is closely related with PTZ-induced epileptic seizures and that STX1B might be a protein marker in a PTZ-induced seizure model for the screening of anticonvulsant drugs." (PMID 30534049, 2018). "However, the correlation of STX1B to photosensitive epileptic seizures has not been reported until now." (PMID 30534049, 2018).
Alzheimer disease (1 paper, 2018). A progressive, neurodegenerative disease characterized by loss of function and death of nerve cells in several areas of the brain leading to loss of cognitive function such as memory and language. "We uncovered several promising tissue-specific regulatory TFs or genes for Alzheimer’s disease (e.g. ZIC1 and STX1B) and asthma (e.g. CSF3 and IL1RL1)." (PMID 29378629, 2018).
asthma (1 paper, 2018). "We uncovered several promising tissue-specific regulatory TFs or genes for AD (e.g. ZIC1 and STX1B) and asthma (e.g. CSF3 and IL1RL1) in our case studies." (PMID 29378629, 2018).
Burkitt lymphoma (1 paper, 2022). A rare form of malignant mature B-cell non-Hodgkin lymphoma. "As demonstrated, the Stx1B-scFv OKT3 promotes up to 93% of Burkitt’s lymphoma-derived tumor cells elimination within 48 h and 90% of solid tumor cells lysis at 72 h post-treatment." (PMID 36494671, 2022). "This prompted us to first investigate the anti-tumor activity of the Stx1B-scFv OKT3 lectibody in Burkitt's lymphoma-derived cell lines." (PMID 36494671, 2022). "Similarly to the results observed for Burkitt ́s lymphoma-derived cells, the Stx1B-scFv OKT3 lectibody could not recognize Gb3-depleted tumor cells." (PMID 36494671, 2022).
colon adenocarcinoma (1 paper, 2022). "Firstly, we characterized two human colon adenocarcinoma cell lines—HT-29 and LS-174—for the abundance of Gb3 antigen at their plasma membrane by using fluorescently labelled Stx1B-Cy5." (PMID 36494671, 2022).
colon cancer (1 paper, 2022). "The binding of the lectibody to the PPMP-treated cells decreased drastically from from 75.4 to 0.34%, which validates the specificity of Stx1B-scFv OKT3 towards Gb3+ colon cancer cells." (PMID 36494671, 2022).
colorectal cancer (1 paper, 2021). A primary or metastatic malignant neoplasm that affects the colon or rectum. "First, the colorectal cancer cell lines HT-29 and Caco-2 were tested for the expression of the Gb3 receptor (for Stx1B), while HeLa cells were included as a control, as they are known to express Gb3 and bind Stx1B." (PMID 33499141, 2021).
dementia (1 paper, 2022). Loss of intellectual abilities interfering with an individual's social and occupational functions. "Within the neurodegenerative group, two proteins (VKORC1 and STX1B) were shared between AD and PD, and two other proteins (QPCT and CD2AP) were shared between the clinical diagnosis of AD and AD based on both clinical diagnosis and family history of dementia." (PMID 35882878, 2022).
focal epilepsy (1 paper, 2018). A seizure caused by a localized disorder. "Some syndrome-specific associations were detected, such as the relatively strong signal for STX1B in JME, and the association of GJA1 with focal epilepsy-hippocampal sclerosis." (PMID 30531953, 2018).
photosensitive epilepsy (1 paper, 2018). An epilepsy characterized by seizures triggered by visual stimuli that form patterns in space or time, such as flashing lights. "In association with our results, these studies imply that STX1B may be associated with photosensitive epilepsy." (PMID 30534049, 2018). "Since both stx1b and chd2 gene mutations can lead to MAE, whether or not STX1B is also related to photosensitivity epilepsy like CHD2 is, remains a question." (PMID 30534049, 2018). "Whether STX1B is involved in photosensitive epilepsy or not has to our knowledge, not yet been reported on." (PMID 30534049, 2018).